RBP4 (retinol binding protein 4)
Diseases named in the same sentence as RBP4 in open-access papers (continued):
Sharing a sentence is not in itself a finding about the gene and the disease.
Insulin resistance (continued). "Increasing serum RBP4 concentrations causes insulin resistance, by transgenic overexpression or by injection of purified RBP4 protein into wild-type mice." (PMID 25890223, 2015). "RBP4 is the only specific transport protein for retinol (vitamin A) in the circulation, and elevation of serum RBP4 causes systemic insulin resistance." (PMID 25918733, 2015). "RBP4 is elevated in association with insulin resistance in diet-induced obesity and genetically obese (ob/ob) mouse models." (PMID 25918733, 2015). "VEGFA stimulates angiogenesis in adipose tissue,SERPINE4 belongs to pro-inflammatory adipokines, and RBP4 is associated with insulin resistance and visceral fat distribution." (PMID 25887648, 2015). "NLaz is an ortholog of the vertebrate lipocalins – lipocalin 2 and retinol binding protein 4 (RBP4) – which modulate peripheral insulin resistance and have been associated with metabolic homeostasis." (PMID 24609035, 2014). "Multiple single nucleotide polymorphisms (SNP) of RBP4 were also discovered in the human genome, which predict the susceptibility to insulin resistance, obesity, and type 2 diabetes." (PMID 26237385, 2014). "In humans, several studies have also shown positive associations between RBP4 and insulin resistance as well as features of MetS." (PMID 24559154, 2014). "Retinoic acid signaling components (retinol binding protein 4, retinal, retinoic acid and retinoid receptors) have been implicated in modulating the development of obesity, insulin resistance and diabetes." (PMID 26237391, 2014). "In recent years, RBP4 has been proposed to be a cardiometabolic risk factor associated with T2D, obesity and hyperlipidaemia and it appears to induce insulin resistance in skeletal muscle, liver and adipose tissue in vitro." (PMID 24800810, 2014). "In participants with various clinical presentations, serum RBP4 has been positively correlated with insulin resistance and is an important adipokine associated with type 2 diabetes and cardiovascular complications." (PMID 24475021, 2014). "In spite of the rather established relation to insulin resistance and cardiovascular risk factors, the actual association of RBP4 levels with atherosclerotic-related cardiovascular disease is still controversial." (PMID 25142320, 2014). "Future studies on the potential impact of RBP4 on metabolic risk in RA should include markers of insulin resistance such as the homeostasis model assessment of insulin resistance." (PMID 24651174, 2014). "Several RBP4 gene variants are associated with adiposity, the predisposition to visceral accumulation of adipose tissue, insulin secretion or/and insulin resistance and type 2 diabetes." (PMID 24651174, 2014). "Proteomic analysis yielded seven proteins which decreased significantly after GBP only, including Fetuin-A and Retinol binding protein 4, both previously linked to insulin resistance." (PMID 24800810, 2014). "Clinical studies have also reported that circulating RBP4 levels are associated with insulin resistance in subjects with obesity, impaired glucose tolerance, or type 2 diabetes as well as in nonobese subjects." (PMID 24733068, 2014). "In summary, our findings suggest greater lowering of multiple proteins including RBP4, Fetuin-A as well as several metabolites associated with insulin resistance following GBP compared with SG prior to diabetes remission." (PMID 24800810, 2014). "Several RBP4 gene variants have been identified that associate with the accumulation of adipose tissue, insulin resistance, and T2D." (PMID 25479076, 2014). "Transgenic overexpression of human RBP4 or injection of recombinant RBP4 in normal mice causes insulin resistance and glucose intolerance." (PMID 24160775, 2013). "In humans, adipose tissue and circulating RBP4 levels are associated with obesity, insulin resistance, type 2 diabetes and components of the metabolic syndrome, although it should be emphasized that these associations were not shown consistently." (PMID 23460908, 2013).
Insulin resistance (continued). "Previous studies involving healthy participants support associations between RBP4 and insulin resistance." (PMID 23936766, 2013). "Lipocalin-2 (also known as 24p3, neutrophil gelatinase-associated lipocalin and siderocalin) and retinol binding protein 4 (RPB4) are novel adipokines that contribute to insulin resistance and type 2 diabetes in obese rodents." (PMID 23799122, 2013). "RBP4 not only transports retinol in the bloodstream, but also has been linked to insulin resistance in both rodent and human models." (PMID 23840311, 2013). "RBP4 is considered to be secreted from adipocytes in response to declining blood glucose levels and to cause insulin resistance and thereby counter regulate hypoglycemia." (PMID 23781325, 2013). "At the same time, other studies reporting a relationship between plasma levels of RBP4 and triglycerides have detected a strong link with insulin resistance and an independent association of triglyceride levels and insulin resistance with RBP4." (PMID 24223837, 2013). "Recent studies in human found that plasma RBP4 levels were elevated in subjects with IGT or type 2 diabetes mellitus and that RBP4 was related to various clinical parameters known to be associated with insulin resistance." (PMID 24160775, 2013). "The association between blood RBP-4 concentrations and insulin resistance is influenced by many confounders including age, BMI, disease status, nutrition status, genetic factors, and others." (PMID 24367155, 2013). "Whereas low circulating ghrelin has been associated with elevated fasting insulin and insulin resistance in humans, the opposite is true for RBP4." (PMID 23840311, 2013). "In fact, many human studies have found a strong relationship between RBP4 and triglycerides, some finding an association with insulin resistance and others failing to do so." (PMID 24223837, 2013). "In conclusion, the expression of an adipokine implicated in the development of whole body insulin resistance, RBP4, is downregulated by an inflammatory micro-environment in adipose tissue." (PMID 23460908, 2013). "Previous clinical studies have reported that RBP4 is associated with the extent of systemic insulin resistance and obesity." (PMID 23671852, 2013). "Mice with mutations in the catalytic SET-domain of MLL3 show altered gene expression of a number of metabolic genes in adipose tissue, such as Rbp4, which is associated with insulin resistance in human beings." (PMID 24004477, 2013). "For example, high plasma retinol-binding protein (RBP4) has been reported to be associated with the pathogenesis of insulin resistance in type 2 diabetes." (PMID 24283668, 2013). "In this study, we investigated the effect of PPARγ and RBP4 polymorphisms on body mass, insulin resistance and dyslipidemia among HIV-infected patients with anti-retroviral therapy (HAART)." (PMID 23145084, 2012). "In mice, transgenic expression of RBP-4 caused insulin resistance, and RBP-4 knockout mice display enhanced insulin sensitivity." (PMID 22272381, 2012). "For the −803GA polymorphism in RBP4, patients with the A allele (23.1%) more often had insulin resistance (HOMA>3.8; 33.3 vs. 8.7%, P = 0.01) and more often received anti-hypoglycemic drugs (14.3 vs. 1.4%, P = 0.04)." (PMID 23145084, 2012). "Antiretroviral therapy in HIV-infected patients has been reported to induce a pronounced increase of plasma RBP4, which is associated with obesity, insulin resistance and dyslipidemia." (PMID 23145084, 2012). "Elevated serum level of retinol-binding protein 4 (RBP4) has been associated with obesity-related co-morbidities including insulin resistance, dyslipidemia and hypertension." (PMID 23119072, 2012). "In humans, increases of circulating RBP-4 are strongly associated with insulin resistance in adipose tissue, and elevations of circulating RBP-4 are predictive of a diagnosis of metabolic syndrome." (PMID 22828276, 2012).
Insulin resistance (continued). "Increased circulating concentrations of RBP-4 have been linked with increased visceral adiposity and have been shown to directly contribute to hepatic insulin resistance via induction of hepatic glucose production and impairment of insulin signaling in muscle." (PMID 22828276, 2012). "RBP4, a cytokine secreted by adipose tissue, is a novel adipokine linked with obesity and insulin resistance of type 2 diabetes." (PMID 22363757, 2012). "Previous studies have associated serum RBP4 levels to obesity, insulin resistance and components of the metabolic syndrome." (PMID 23119072, 2012). "Serum concentration of both lipocalins correlate with obesity, T2D and insulin resistance in human and mice, although some of these associations have been disputed in human patients in the case of RBP4." (PMID 22567167, 2012). "Our study revealed that the A allele of RBP4 −803GA polymorphism was associated with insulin resistance in HIV-infected patients receiving HAART." (PMID 23145084, 2012). "The detrimental effect of the A allele in RBP4 −803GA polymorphism on development of insulin resistance was supported by the multivariate analysis adjusting for covariates." (PMID 23145084, 2012). "RBP4 −803GA polymorphism has increased risk of insulin resistance in HIV-infected patients with anti-retroviral therapy." (PMID 23145084, 2012). "In conclusion, the A allele of −803GA polymorphism in RBP4 is associated with a higher rate of insulin resistance." (PMID 23145084, 2012). "Elevated plasma levels of RBP4 have been implicated in the development of the metabolic syndrome and insulin resistance, and have been inversely correlated with adipocyte glucose transporter 4 (GLUT4) protein levels." (PMID 20559430, 2010). "Initial studies linked elevated serum RBP4 to overt or impending insulin resistance in lean, obese and type 2 diabetic subjects." (PMID 20932285, 2010). "Using the adipose-specific Glut4 knockout (adipose-Glut4(−/−)) mice model, retinol-binding protein 4 (RBP4) has been identified as a highly expressed circulating adipokine that causes insulin resistance when it is overexpressed or injected into mice." (PMID 20847813, 2010). "Increased circulating concentrations of chemerin, progranulin, RBP4, and fetuin-A have been shown to be associated with insulin resistance." (PMID 21085476, 2010). "Elevated serum RBP4 concentrations were an independent predictive biomarker at early stages of insulin resistance identifying individuals at risk of developing diabetes and were even found in healthy individuals with a strong family history of type 2 diabetes." (PMID 20932285, 2010). "Apart from its role as a retinol transporter, RBP4 has also been implicated in causing insulin resistance in muscle and liver." (PMID 20625434, 2010). "It is well established that the liver is the main source of RBP4 in humans, although adipocyte RBP4 secretion has been linked to obesity, insulin resistance and type 2 diabetes." (PMID 20932285, 2010). "A large number of subsequent studies confirmed there was an association between increases in the circulating RBP4 levels and various aspects of adiposity, insulin resistance, diabetes mellitus, and metabolic syndrome." (PMID 20847813, 2010). "This association of serum RBP4 to endogenous insulin secretion and insulin resistance was in sharp contrast to other adipocytokines." (PMID 20932285, 2010). "Systemic insulin resistance has been associated with elevation of serum RBP4, whereas genetic and pharmacological interventions aimed at decreasing serum RBP4 levels enhance insulin action and improve insulin sensitivity." (PMID 19460132, 2009). "Additionally, protein RBP4, a well-known adipokine associated with insulin resistance in T2D, and mucin (MUC7) were upregulated, serving as quality controls for our analysis." (PMID 39794871, 2025).
Insulin resistance (continued). "Consequently, RBP4 levels are elevated in serum and adipose tissue in cases of obesity-induced insulin resistance and are linked to metabolic syndromes." (PMID 41144502, 2025). "The higher RBP4 in SA HDL corroborates SA predisposition to insulin resistance and may contribute to this phenotype." (PMID 41416660, 2025). "Additionally, RBP4 levels are elevated in the serum and adipose tissue of individuals with obesity-induced insulin resistance and are associated with other metabolic syndromes." (PMID 41144502, 2025). "This parallels glucose metabolism-related gene regulation, implying that RBP4 expression might be part of a network linked to insulin resistance development." (PMID 39698033, 2024). "Although most studies and many independent laboratories have confirmed that circulating RBP4 levels are elevated in IR and type 2 diabetic states, the underlying cause of this elevation and whether RBP4 actively promotes insulin resistance remain unclear." (PMID 39698033, 2024). "Vaspin plays a protective role in obesity via its insulin-sensitizing and anti-inflammatory effects, and RBP4 is contrarily involved in the development of insulin resistance and associated with total cholesterol and triglyceride levels, contributing to the progress of obesity." (PMID 38256272, 2024). "TTR may have other functions with significance for marine mammal stress physiology, as it also transports RBP4, an adipokine associated with insulin resistance." (PMID 39498350, 2024). "They concluded that reductions in circulating RBP4 may improve insulin resistance in morbidly obese individuals after weight loss." (PMID 38520616, 2024). "Moreover, mediation analyses suggested that the lipid-HUA associations were partially mediated by retinol-binding protein 4 (RBP4, mediation proportion 5–14%), an adipokine linked with dyslipidemia and insulin resistance." (PMID 39583309, 2024). "Increasing evidence suggests that RBP4 induces insulin resistance (IR) and is closely associated with diabetes mellitus (DM), obesity, metabolic syndrome (MS), hyperuricaemia (HUA), non-alcoholic fatty liver disease (NAFLD), hypertension (HTN), and cardiovascular diseases (CAD)." (PMID 39698033, 2024). "Additionally, the presence of MAFLD showed a significant correlation with adipocytokines associated with insulin resistance, such as adiponectin, leptin, and retinol-binding protein-4 (RBP-4) levels (all p < 0.001)." (PMID 37854195, 2023). "In vitro studies on human adipocytes and serum showed that elevated RBP4 levels in morbidly obese patients may promote insulin resistance through lipolysis and macrophage activation causing a pro-inflammatory cytokine release." (PMID 36983885, 2023). "Serum retinol-binding protein, which is a 21-kD protein produced in the liver and adipose tissue, acts primarily as a transporter of retinol or vitamin A. RBP4 is an adipocyte-secreted hormone that is enhanced in insulin resistance associated with obesity and also induces insulin resistance." (PMID 35629362, 2022). "Moreover, the overexpression of RBP4 or recombinant RBP4 injection induces insulin resistance, whereas RBP4 deficiency increases insulin sensitivity." (PMID 35909571, 2022). "Obesity and insulin resistance are associated with elevated RBP4 levels in the blood." (PMID 36030930, 2022). "Recent evidence suggests that it may function as anadipokine associated with metabolic homeostasis and elevated RBP4 levels areassociated with insulin resistance." (PMID 39076230, 2022). "It is worth mentioning that RBP4 is a well-associated marker of insulin resistance." (PMID 36558360, 2022). "Given the close association between elevated RBP-4 levels and glycaemic metabolism and insulin resistance in T2DM patients, longitudinal studies are needed to investigate how these changes in RBP-4 levels occur, especially in T2DM patients predisposed to these conditions." (PMID 35547000, 2022).
Insulin resistance (continued). "Several studies also declared null association between RBP4 and insulin resistance." (PMID 35634496, 2022). "Although insulin resistance was rarely associated with acute graft-versus-host disease, based on our analysis, it is possible that RBP4 may have attracted macrophages to the adipocytes causing adipose tissue inflammation, thus damage to muscle and fat tissue." (PMID 35977993, 2022). "Both of the in vivo experiments showed that the elevated serum RBP4 caused insulin resistance." (PMID 34944728, 2021). "Moreover, transgenic overexpression of human RBP4 or injection of recombinant human RBP4 in wild-type mice caused glucose intolerance and insulin resistance." (PMID 33790810, 2021). "Deficiencies in RBPR2 might play a role in the development of insulin-resistant phenotypes given the protein’s interaction with RBP4, in which an excess of holo-RBP4 is linked to insulin resistance and glucose intolerance." (PMID 34836244, 2021). "However, the serum levels of retinol-binding protein 4 (RBP4) were negatively associated with insulin resistance (IR) in pregnancies with GDM." (PMID 33572656, 2021). "Clinical evidence suggests that RBP4 is associated with hepatic steatosis and insulin resistance." (PMID 34944728, 2021). "Therefore, this study was conducted to find the association between retinol-binding protein-4 with insulin resistance and the severity of coronary artery disease." (PMID 34571734, 2021). "RBP4 could contribute to insulin resistance, and high levels of circulating RBP4 are associated with atherosclerosis and CAD." (PMID 34130657, 2021). "Therefore, RBP4 overexpression causes insulin resistance, while the reduced expression ameliorates insulin resistance." (PMID 32116650, 2020). "Plasma RBP4 concentrations in the first and second trimester were associated with fasting insulin, homeostasis model assessment for insulin resistance (HOMA-IR), and the quantitative insulin sensitivity check index (QUICKI) in the second trimester (all P < 0.001)." (PMID 31921323, 2020). "RBP4 levels were closely associated with insulin resistance." (PMID 31956345, 2020). "Thus, it has been proposed that functional RBP4 gene polymorphisms influence a higher obesity incidence, insulin resistance, hyperinsulinemia, T2DM, and artery thickness." (PMID 32718041, 2020). "In addition, insulin resistance is caused by inhibition of GLUT4 due to excessive expression of RBP-4 (retinol binding protein-4) in abnormal adipose tissue." (PMID 32481506, 2020). "Thus, adipocyte iron induces expression of the insulin-inhibitory adipokines resistin and RBP-4 (retinol-binding protein 4), causing insulin resistance." (PMID 33096618, 2020). "In addition, plasma RBP4 in the first and second trimester is associated with insulin resistance in the second trimester." (PMID 31921323, 2020). "However, recent research has identified adipocytes as another source of RBP4, and evidence from animal and human studies has implicated the involvement of RBP4 in the pathogenesis of insulin resistance and type 2 diabetes." (PMID 30651745, 2019). "Although retinol binding protein 4 (RBP4) has been implicated in insulin resistance in experimental studies, the association between RBP4 and risk of type 2 diabetes remains unclear." (PMID 30651745, 2019). "However, RBP4 is also considered to be an adipokine, as it has been implicated in the pathogenesis of insulin resistance." (PMID 31717719, 2019). "Retinol binding protein 4 (RBP4), mainly secreted by the liver and adipocytes, is a transporter of vitamin A. RBP4 has been shown to be involved in several pathophysiological processes, such as obesity, insulin resistance, and cardiovascular risk." (PMID 31412686, 2019). "Interestingly, APLN is a known adipokine implicated in coagulation, insulin resistance and diabetes and its higher expression in layers is consistent with the pattern of another pro-inflammatory adipokine in mammal, RBP4." (PMID 29695257, 2018).